TRIB1 (tribbles pseudokinase 1)
Diseases named in the same sentence as TRIB1 in open-access papers (continued):
Sharing a sentence is not in itself a finding about the gene and the disease.
tumor (continued). "In this study, we showed that TRIB1 increased GBM cell survival through ERK and Akt, which are central regulators of pathways involved in tumor maintenance and growth of GBM cells." (PMID 37528172, 2023). "Similarly, 25% of cells in the murine tumor expressed high levels of TRIB1 and 85% of these were also positive for the mouse macrophage marker F4/80, together suggesting a potential role for macrophage TRIB1 in regulating tumorigenesis in BC, both in human and murine tumors." (PMID 35664073, 2022). "This contrasts with the oncogenic role of TRIB1 in MEK1/ERK signalling, suggesting TRIB2 acts as a tumour suppressor by promoting the activation of stress-activated, rather than proliferative, MAPK pathways in response to stress." (PMID 34205360, 2021). "By targeting transforming growth factor-alpha (TGF-α), tribbles pseudokinase 1 (TRIB1), CCND2, and high-mobility group AT-hook 2 (HMGA2) and Src, miR-203, miR-224, miR-154, and miR-1, respectively, counteract EMT, tumor progression and metastasis." (PMID 33805590, 2021). "To explore its expression in CRC, we detected TRIB1 protein level in 8 pairs of CRC tumor and surrounding non-tumor tissues by western blotting." (PMID 28624785, 2017). "Higher expression of TRIB1 protein was detected in 58/83 (69.9%) of CRC tissues, compared with adjacent non-tumor tissues." (PMID 28624785, 2017). "Overexpression of TRIB1 was detected in 52/75 (69.3%, P<0.05, Wilcoxon's signed-rank tests) of CRC as compared with adjacent non-tumor tissues." (PMID 28624785, 2017). "Nevertheless, knockout of myeloid-TRIB1 upregulates the expression of oncogenic cytokines in TAMs whilst its overexpression modifies TAM phenotype and T-cell composition in the TME, both enhancing tumor growth." (PMID 35664073, 2022). "According to the changes of the expression status of differential molecules between the two networks, we identified the top 10 differential mRNAs (PRKAA2, NLGN4X, ST6GALNAC3, DGAT1, TRIB1, GRPR, and MLLT11) and lncRNAs (n339695, n378130, and n410438) in the tumor–endothelium interaction." (PMID 33681194, 2021). "Consistent with previous reports describing tumor-derived EVs, immune checkpoints CD47 and CD274/PD-L1, and key regulators of myeloid differentiation (e.g., TRIB1, SOCS3, STAT3) were upregulated in EwS EV-treated cells compared to control, with TC32 EVs generally eliciting stronger effect." (PMID 34440851, 2021). "Specifically, TRIB1 and TRIB3 might be considered candidates as predictive markers of tumor metastasis development." (PMID 34198908, 2021). "Increasing TRIB1 expression in these PC3 cells has been shown to promote tumour growth, whereas increasing TRIB1 in DU145 cells did not." (PMID 34572744, 2021). "With regards to PCa, the evidence on the function of TRIB1 is limited, and no genetically engineered mouse models have been generated to provide formal demonstration of its tumor-promoting activity." (PMID 32932846, 2020). "In line with our in vitro results, ectopic TRIB1 expression did not elicit a significant effect on tumor growth." (PMID 32932846, 2020). "In addition, IHC was used to examine TRIB1 expression in 75 pairs of CRC tissues and matched adjacent non-tumor tissues." (PMID 28624785, 2017). "In addition, we examine the protein expression of TRIB1 in a series of CRC and adjacent non-tumor tissues using western blotting and IHC." (PMID 28624785, 2017). "TRIB1 and TRIB2 have potent oncogenic activities in vertebrate cells, and recent evidence also suggests that TRIB2 acts as a tumour suppressor, consistent with the requirement for balanced TRIB signaling in the regulation of transcription, differentiation, proliferation, and apoptosis." (PMID 27908682, 2017). "In addition, TRIB1 upregulation activates β-catenin and its effectors, promoting EMT and tumor metastasis." (PMID 29176948, 2017).
tumor (continued). "Thus, this in vivo experiment showed that TRIB1 overexpression enhanced tumor growth, which involved TRIB1-MEK1 interaction, suggesting that TRIB1 may serve as a druggable target in GBM." (PMID 37528172, 2023). "It was not until 2017 that the TRIB1 gene was shown to be amplified and overexpressed in CRC tissues, when compared with paired surrounding non-tumor tissues from the same patients." (PMID 34198908, 2021). "Moreover, many genes (PTN, SIAH2, FAM111B, TMEM43, FOSL2, TRIB1 and SPATA1) were hypomethylated regardless of tumor grade." (PMID 36850002, 2023).
cardiovascular disease (9 papers, 2015 to 2026). "Recent reports have shown that polymorphisms in the TRPS1 and TRIB1 genes are associated with plasma lipid levels and the risk of cardiovascular disease." (PMID 41972583, 2026). "Numerous clinical studies have shown an association between polymorphisms of the PON1 and TRIB1 genes and various cardiovascular diseases." (PMID 39062650, 2024). "The rs2954029 and rs17321515 polymorphisms of the TRIB1 gene were studied in patients with circulatory system diseases." (PMID 39062650, 2024). "The regulatory effects of TRIB1 on circulating lipids and immune cells suggest that TRIB1 is associated with the development of cardiovascular diseases." (PMID 34539875, 2021). "So far, several studies have investigated the independent effects of coffee intake and TRIB1 rs17321515 on cardiovascular disease risk." (PMID 32370221, 2020). "In humans, TRIB1 in liver regulates hepatic lipid metabolism and is associated with increased liver fat content and cardiovascular disease." (PMID 32562350, 2020). "Subsequent abundant studies had shown that TRIB1 rs17321515 and rs2954029 were significant associated with the dysregulation of serum lipids levels and the risk of cardiovascular disease." (PMID 30851741, 2019). "In consideration of the tight association of NAFLD with the dysregulation of lipids metabolism and the risk of cardiovascular disease, it is meaningful to explore the effect of TRIB1 rs17321515 and rs2954029 in the NAFLD patients." (PMID 30851741, 2019). "TRIB1 is also involved in macrophage polarization, inflammatory factor regulation, and fat synthesis, linking inflammation and cardiovascular disease." (PMID 34539875, 2021). "TRIB1 knockout leads to metabolic disorders and cardiovascular disease by affecting the repair of M2 macrophages." (PMID 34539875, 2021). "There is no doubt about the significant role of TRIB1 rs17321515 and rs2954029 in the lipid metabolism and the risk of cardiovascular disease." (PMID 30851741, 2019). "We speculate that TRIB1 may be a favorable factor in cardiovascular diseases." (PMID 34539875, 2021). "We predicted 6 candidate genes (PANK1, TRIB1, BMPR2, HDAC9, THBS1, and LARP1) that might bind to miR-942-5p and played a role in cardiovascular disease." (PMID 33869307, 2021).
metabolic disorders (7 papers, 2018 to 2024). "Moreover, in metabolic disease, single-nucleotide polymorphisms (SNPs) at the TRIB1 locus were found to be associated with cholesterol and LDL-C levels." (PMID 35205759, 2022). "Trib1 is a critical factor for adipose tissue maintenance and the suppression of metabolic disorders that act by controlling the differentiation of tissue-resident M2-like macrophages." (PMID 32265926, 2020). "Trib1 is a key switch for adipose tissue maintenance and metabolic disorder inhibition that functions by modulating the polarization of tissue-resident M2-like macrophages." (PMID 32265926, 2020).
infection (5 papers, 2012 to 2024). The state of being infected such as from the introduction of a foreign agent such as serum, vaccine, antigenic substance or organism. "While TRIB1 has been shown to regulate several inflammatory and innate immune functions in vitro, its role in infection is much less characterised, especially in an in vivo setting." (PMID 38896446, 2024). "The pseudokinase Tribbles1 (Trib1) regulates multiple innate immune processes and inflammatory profiles making it a potential drug target in infections." (PMID 38896446, 2024). "Together our findings show a potential therapeutic application of targeting Trib1 to improve infection outcomes." (PMID 38896446, 2024). "Infection resulted in 67-fold (± 13) and 153-fold (± 46) upregulation in TRIB1 message for 293T and HeLa cells respectively." (PMID 27019349, 2016). "For example, overexpression of TRIB1 in chronic mycobacterial infections may be beneficial against infection, but could trigger immunopathology." (PMID 38896446, 2024). "Further research into TRIB1 as a target for host-derived therapies could potentially improve infection outcome of mycobacterial infection via pharmacological targeted delivery methods and transient manipulation through genetic approaches." (PMID 38896446, 2024). "We also used qRT-PCR to validate the pre-clinical over-expression of 4 of these genes previously unrecognized as playing a role in prion pathobiology; RASGRF2, TRIB1, MCL1 and HOMER1 were all confirmed to be up-regulated during the same time period post-infection in CA1 pyramidal neurons." (PMID 23144617, 2012).
bacterial infection (3 papers, 2013 to 2024). "Our research is the first demonstration that SHIP can indirectly regulate the expression of Trib1 through altering STAT5 activation to mediate the function of macrophages, which may provide significant insight into development of novel therapeutics to conquer bacterial infection." (PMID 32256487, 2020).
heart diseases (1 paper, 2025). "As observed, the distribution of TRSP1 and TRIB1 polymorphisms is different compared with other populations, so we suggest that the impact of these SNPs on ACS and other heart diseases should be studied in larger research projects that include patients from various backgrounds." (PMID 40563858, 2025).
renal disease (1 paper, 2018). "Trib1-ROSA-Mb1 mice did not display any symptom of lupus disease: activation status of Bcells is normal, and we did not detect any feature of renal disease." (PMID 29599769, 2018).
TRIB1 also shares sentences with these, for which no sentence is quoted: myeloid leukemia (4 papers); acute megakaryocytic leukaemia (2); age-related macular degeneration (2); Cirrhosis (2); COVID-19 (2); Crohn disease (2); Hypercholesterolemia (2); infertile (2); acute kidney injury (1); acute leukemia (1); adenocarcinoma (1); alcoholic fatty liver disease (1); Alzheimer disease (1); Anxiety (1); aortic stenosis (1); asthma (1); chronic kidney failure (1); coronary atherosclerosis (1); essential hypertension (1); fibrosis (1); follicular thyroid cancer (1); ganglioglioma (1); glioblastoma (1); gout (1); hand osteoarthritis (1); hematological disorders (1); HTLV infection (1); immune disorders (1); Insulin resistance (1); ischemic stroke (1).
A further 13 diseases each share a sentence with TRIB1 in 1 paper.